TNF (tumor necrosis factor)
Diseases named in the same sentence as TNF in open-access papers (continued):
Sharing a sentence is not in itself a finding about the gene and the disease.
infection (continued). "This cascade increased the secretion of TNF-α and IL-1β compared with the untreated C. albicans-infection group." (PMID 41031111, 2025). "The combination of TA:SeCA coated catheter segments with GSNO and GSH resulted in substantial reductions in key pro‐inflammatory cytokines, TNF‐α and IL‐6, highlighting its potential to mitigate inflammation, infection, and thrombosis." (PMID 40879081, 2025). "Of course, safety and efficacy would need thorough evaluation—prior trials in other cancers have had mixed results, and TNF-α blockade can carry risks (e.g., infection)." (PMID 40299527, 2025). "The results demonstrated that infection of RAW 264.7 cells with M. smegmatis led to increased production of the pro-inflammatory cytokines TNF-α and IL-1β." (PMID 40005637, 2025). "In the serum of goats infected with F. hepatica, the level of TNF-α gradually increased throughout the infection process." (PMID 39858178, 2025). "Specifically, infected mice exhibited a notable increase in proinflammatory cytokines, including MCP-1, IFN-γ, IL-12p70, TNF-α, and IL-6, particularly at 10 days post-infection (dpi)." (PMID 40078875, 2025). "TNF- α and IL-1β contribute to the generation of protective immunity against infection with H. capsulatum." (PMID 40558960, 2025). "During infection, heightened immune activity elevates pro-inflammatory cytokines such as tumor-necrosis factor-α (TNF-α) and interleukin-6 (IL-6) within the uterine environment." (PMID 40868898, 2025). "Whereas during established infection, TNF production is required for the maintenance of a robust immune response to the infection by immune cells." (PMID 38459711, 2024). "infection, there are characteristic dynamics in serum levels of TNF-α and IL-10 during the development of the disease." (PMID 39770719, 2024). "Our report is the first to show the expression profile of inflammatory biomarkers (IL-1β, IL-6, TNF-α, IL-18) in four tissues after infection with L. europaeus—with two genotypes simultaneously." (PMID 39273479, 2024). "Afterward, as determined by WB analysis, the protein levels of junction complexes sharply decreased in HUVECs under TNF-α treatment, followed by IP-10 treatment conditions and finally CV-A16 infection conditions." (PMID 39559356, 2024). "Cytokines such as IL-1β and TNF produced following infection were shown to directly inhibit the dorsal raphe nucleus in the brain, which is responsible for wakefulness and to activate the POA/basal forebrain region that promotes nonrapid eye movement sleep." (PMID 39107476, 2024). "Macrophages exposed to 2-AA in the presence of exogenous ATP showed improved intracellular bacterial clearance and enhanced TNF-α levels, supporting the epigenetic interconnection of macrophages and cellular ATP responsiveness levels against infection." (PMID 39269443, 2024). "Investigators have shown that prior Ts infection can protect against cytokine shock induced by TNF-α and IFN-γ." (PMID 38899916, 2024). "This leads to an upregulation of IFN‐γ, IL‐6, TNF‐α, and other cytokines and chemokines, ultimately improving infection control and survival rates." (PMID 39492834, 2024). "Even so, in an animal model, (from 15 to 120 days after infection) TNF-α production was shown to be persistent in the heart throughout infection." (PMID 39598539, 2024). "The levels of IL-1β, IL-6, IFN-γ and TNF-α in the PCV4-inoculated group remained elevated throughout the infection period." (PMID 39135875, 2024). "The iNOS is one of nitric oxide synthesis (NOS) enzymes that catalyzes NO production, and COX-2 regulates the production of NO and pro-inflammatory cytokines such as IL-6, IL-1β, and TNF-α to facilitate pathogen clearance during infection." (PMID 38213288, 2024).
infection (continued). "The anti-PySRA-F2 antibody can protect mice against P. yoelii, and the pro-inflammatory responses such as IL-1β, TNF-α, and IL-6 after infection with P. yoelii are attenuated." (PMID 38624215, 2024). "Interleukin-1β (IL-1β), IL-6, and tumor necrosis factor-α (TNF-α) are potent proinflammatory cytokines involved in the host defense against infection and injury." (PMID 39456209, 2024). "Although visually, CXCL10 and TNF levels also appeared lower after the third infection, we were unable to detect a statistically significant difference, potentially because of the small sample size." (PMID 39666392, 2024). "The incidence of infection in patients receiving baricitinib was comparable to those receiving TNF inhibitors." (PMID 39480594, 2024). "This case underscores the need for further research into prophylactic treatment and monitoring protocols to manage recurrent infections during anti-TNF-α therapy effectively." (PMID 38883009, 2024). "The authors found that up to 18 days post-infection, there was a significant production of TNF-α and IL-10 levels from dogs’ leucocytes and splenocytes, but this difference disappeared after 30 days." (PMID 39770719, 2024). "These cells exhibited effector and central memory phenotypes, similar to natural infection and after vaccination, potentially sustained by IL-2 and TNF-α, crucial for memory T-cell proliferation and survival." (PMID 39763646, 2024). "In the case of TNF-α, our studies show an increase in the relative expression of mRNA only during infection with the GI.1 genotype (1.9-fold change, p = 0.02 vs. control)." (PMID 39273479, 2024). "In summary, our findings have enhanced our knowledge of the extent and molecular basis in which TNF is involved in ADMD and susceptibility to infection." (PMID 38459711, 2024). "In line with our observations, IgA deficiency has been shown to lead to a delayed adaptive immune response to Mtb infection, and IgA-deficient mice ineffectively controlled infection against a background of reduced IFN-γ and TNF production by T cells." (PMID 38799462, 2024). "On the other hand, the concentration of TNF-α induced by infection with S2308, RB51, and HKBA was significantly higher compared to the unstimulated group." (PMID 38464511, 2024). "The cytokine tumor necrosis factor alpha (TNFα) is rapidly released after trauma, injury, or infection and acts as a central mediator in the inflammatory response." (PMID 39020149, 2024). "The protective effect of cytokines in the axis IL-12/IFN-γ/TNF-α and IL-1β to control the infection is evident." (PMID 39062562, 2024). "Collectively, these results suggest that the transcriptional environment induced by ΔUL26 infection has similarities to TNFα-treated PIAS1KO cells." (PMID 38768227, 2024). "As the infection progresses, TNF-α coordinates the chemokine response within the lung and facilitates the development of the granuloma." (PMID 38790916, 2024). "In contrast, di-ABZI-stimulated release of IFN-1 by MDM-2 was not statistically significant, even though both MDM-1 and MDM-2 secreted TNFα 1 day post infection when treated with di-ABZI." (PMID 38866980, 2024). "At different time points post infection, we monitored the mRNA level for the cytokines TNF-α, IL-8, IL-12 and IL-18 by qRT-PCR." (PMID 39104852, 2024). "For TNF-α, infection was also able to induce an increase in this cytokine in all groups when compared to the level in the healthy control (p < 0.0079)." (PMID 39598539, 2024). "TNF promotes apoptosis and is a potent proinflammatory cytokine that recruits various immune cells, such as neutrophils and T cells, to the site of infection." (PMID 38892443, 2024). "Using a human cervical tissue explant model, we found that GC inoculation increased the local secretion of both proinflammatory (IL-1β and TNF-α) and antiinflammatory (IL-10) cytokines during the first 24 hours of infection." (PMID 39585777, 2024).
infection (continued). "IL1-β is a pro-inflammatory cytokine and plays a role in the immune response to infections and injury, while TNF-α, also pro-inflammatory, is involved in inflammation and cell death." (PMID 38600563, 2024). "Collectively, these findings indicate that EIIB in L. monocytogenes LIPI-4 stimulates the release of inflammatory factors IL-1β, IL-6, IL-10, and TNF-α to combat infection." (PMID 39057985, 2024). "Th1 polarization of HTLs is essential, since the production of cytokines such as IFN-y and TNF-a responds to primary and secondary infections, respectively." (PMID 38248954, 2024). "As previously shown, MHV-A59 induced the production of TNF in wild-type BMDMs starting from 24 h post-infection." (PMID 39452742, 2024). "Fish TNF-α acts as regulator and amplifier for acute and chronic inflammation, it is one of the early immune genes that is expressed at the early stage of infection." (PMID 39243089, 2024). "Overall, these results suggest that TNF is crucial for inducing chemokine and IL-6 production during craniotomy infection, specifically in the galeal compartment, aligning with previous reports." (PMID 39044282, 2024). "The results showed that 0.5 ml of the viral supernatant infection yielded 15% of the DCs expressing TNF, with similar infection efficacy with chimeric CD66b-Muc1 scFv." (PMID 39105847, 2024). "Although the routes of infection affected protective efficacy of anti-TNF-α Ab treatment, these results suggest that the TNF-α signaling pathway is strongly implicated in the pathogenesis of these models." (PMID 38550855, 2024). "IL-1β, TNF-α, and IL-6 are all upregulated in the context of inflammation and infection and are involved in the pathogenesis of preterm labor." (PMID 38791199, 2024). "Highly-expressed MIR155HG and TNF-α, and complications during hospitalization (infection, blood system damage, renal damage, central nervous system damage, pulmonary damage and cardiac damage) were the risk factors for prognosis of patients." (PMID 38699702, 2024). "In previous studies, HP-PRRSV BB0907 strain infection increased IL-1β, IL-6, TNF-α, and IFN-γ levels in the serum, and infection with the highly pathogenic PRRSV-1 Lena strain increased the serum levels of IFN-γ and IL-6." (PMID 39506759, 2024). "For TNF-α, infection was able to induce an increase in this cytokine in all groups when compared to the level in the healthy control (p < 0.0353)." (PMID 39598539, 2024). "Tumor necrosis factor-alpha (TNF-α) is a pro-inflammatory cytokine that activates immune responses against infection, injury, or inflammation and is involved in the regulation of various immune cells." (PMID 38891863, 2024). "Infection during pregnancy activates the maternal immune system to enhance the production of proinflammatory cytokines, such as IL-6, IL-17, and TNF-α." (PMID 38593153, 2024). "TNF-α, released early after infection, initiates a cascade of inflammatory responses, exacerbating inflammation and worsening the condition." (PMID 38883009, 2024). "Not surprisingly, animals deficient for COX2 showed a strong increase in viral titers in the lung after infection with influenza A virus, whereas the concentrations of cytokines such as TNF, IL-1β, IL-6 and IFNγ were reduced in bronchoalveolar lavage fluid." (PMID 39107476, 2024). "Regarding non–anti-TNF biologics, the infection rate for vedolizumab and ustekinumab that was observed in our cohort is comparable with that reported in other recent studies." (PMID 38305302, 2024). "At 96 h, all drug-treated mice displayed significant decreases (p < 0.01) in the inflammatory markers CXCL1 and TNF-α compared to the positive infection controls, and this was dose-dependent." (PMID 39759447, 2024). "For The TNF Inhibitors group, the most common side effects were infection (7.14%), skin complications (5.95%), and leucopenia (1.19%)." (PMID 39480594, 2024).
infection (continued). "During an active infection, neurodegeneration can result from the persistency of pro-inflammatory markers, such as NO, ROS, IL-1ß, TNF-α, and IL-6 via AP-1 (FosB), NF-кB (RelA/NF-KBI), and Stat1 signaling in microglial cells." (PMID 38731913, 2024). "In contrast, HCV-infected Huh7 cells triggered a TNF-centered immune response, stimulating iMACs to engulf the infected cells and suppress the infection." (PMID 38675895, 2024). "The secreted form of the protein encoded by this gene is known to be increased in response to stress and inflammatory mediators such as IL1B, IFNG, or TNF, as well as upon infection with bacteria and viruses such as SARS-CoV-2." (PMID 39337540, 2024). "They observed that after infection withSARS-CoV-2, endothelialcells from infected lung-on-chips showed significant upregulationof TNF-α, IL6, and IFN-β and more modest increase ininterferon-λ1 (IFNL1) and IFNL3 expression." (PMID 38559954, 2024). "One day after treatment, the fungal load on the palate and dentures, as well as the mean optical density values of IL-17 and TNF-α, were found to be greater in the infection group than in the other three treatment groups (P < 0.05)." (PMID 38708351, 2024). "Meanwhile, Hcrt-1 regulates infection-induced inflammation by modulating the IL-6 and TNF-α in microglia and has a protective role against ischemia stress." (PMID 39839304, 2024). "In contrast, either TNFα-treatment or ΔUL26 infection of PIAS1KO cells strongly induced the expression of these ISGs relative to control cells." (PMID 38768227, 2024). "CA decreased the infection rate by increasing levels of TNF-α, ROS, and NO, and simultaneously decreasing IL-10 levels and iron availability." (PMID 39211053, 2024). "Given the fact that TNF levels in the bloodstream of primates during infections can reach 10–40 ng/mL, the experimental setting of the current study using LT + TNF treatment has reasonably modeled an inflammatory response in B. anthracis-infected animals." (PMID 37855658, 2024). "among anti-TNF, a trend towards a better safety profile of ETN in terms of infection and TB risk resulted from systematic reviews, meta-analyses, and national registries of patients treated with biologics." (PMID 38979406, 2024). "The content of PCT, TNF‐α, and IL‐6 was markedly elevated in infection stage group than the control group (p < .05)." (PMID 38577990, 2024). "In a previous study, we demonstrated in HP-positive patients that thrombin and plasma fragment 1 + 2 production was proportionally related to tumor necrosis factor-alpha levels and that eradication of the infection resulted in a reduction of inflammation." (PMID 38398002, 2024). "Meanwhile, a low level of TNF-α production was detected in PRRSV-infected PAMs at 12–72 h post-infection, suggesting that PRRSV was a weak inducer of TNF-α." (PMID 38962699, 2024). "Subsequently, we assessed the expression levels of the proinflammatory cytokines IL-6 and TNF-α in the cell culture supernatant at 2, 4, and 6 hours post-infection." (PMID 38912723, 2024). "The inflammatory response, often activated as a result of infection, injury, or stress, leads to the release of pro-inflammatory cytokines, such as interleukin-6, tumor necrosis factor-alpha, and interleukin-1 beta." (PMID 39355377, 2024). "In contrast to PCLS, no age-related differences were found in cytokines released by neutrophils and the cytokine response was generally low – only the very early pro-inflammatory cytokines IL-1β and TNFα were detectable 4 h after infection with P. aeruginosa." (PMID 38178102, 2024). "Increased concentrations of TNF within the infection site promote immune cell migration by inducing vasodilation and vascular hyperpermeability." (PMID 38526063, 2024).
infection (continued). "This blockade of type I IFN signaling resulted in greater CD8+ T-cell responses in the DLN at day 5 after RRV-gp33 infection, such that the number of gp33-specific, IFNγ+, TNF+, and GrB+ CD8+ T cells after RRV infection now matched those of LCMV infection." (PMID 39535221, 2024). "Neither clinical strain induced MDM to secrete detectable IFN-I but both induced secretion of TNFα 1 day post infection (Fig. EV2E,F), consistent with the results for the laboratory strain, H37Rv." (PMID 38866980, 2024). "A growing number of studies correlate the levels of type 1 proinflammatory cytokines (IFN-γ, TNF-α), IL-6 and IL-8 post-infection with enhanced disease burden and poor patient outcome, which was in line with the finding in our research." (PMID 38933114, 2024). "Secretion of TNF-α by macrophages and Th1 cells following infection with Newcastle disease virus is a major mediator of viral-induced oncolysis." (PMID 38339315, 2024). "The dilemma arises in balancing PsA control with anti-TNFα therapy while minimizing infection risks." (PMID 38883009, 2024). "During an allergic reaction, these cells would be able to release not only TNF-alpha and other inflammatory mediators but also the virus, exacerbating the infection." (PMID 39768136, 2024). "The research also indicated a significant increase in pro-inflammatory cytokines, such as IL-6 and TNF-α, following acute stress exposure, which is crucial for necessary inflammatory processes during physical injuries or infections." (PMID 39518533, 2024). "The expression of selectins and their ligands is regulated by cytokines, such as interleukin-1 (IL-1) and tumor necrosis factor alpha (TNFα), produced in response to infection and injury." (PMID 39325128, 2024). "In this study, the mRNA expression of pro-inflammatory factors, such as IL-1β and TNF-α, in the liver was found to be dramatically increased after infection." (PMID 39597731, 2024). "M1 macrophages are pro-inflammatory macrophages that clear pathogens and produce inflammatory mediators such as IL-1β, IL-6, and TNF-α during infection and inflammatory responses." (PMID 39123188, 2024). "Knockdown of DARS2, but not related mt-aaRS in BEAS-2B cells significantly attenuated the release of the innate immune cytokines IL-1β, IL-6, and TNFα in response to infection with PA103." (PMID 39039092, 2024). "Excessive production of cytokines (interleukin 6 (IL-6), tumor necrosis factor α (TNFα)) in response to infection can lead to systemic inflammation and CNS manifestations." (PMID 39439614, 2024). "To determine if CETP inhibition regulates proinflammatory cytokine production at the transcriptional level, we examined the mRNA levels of IL-6, IL-1β, and TNF-α using quantitative PCR (qPCR) at 72 hours after infection." (PMID 38646937, 2024). "Our results showed an overall reduction in secretion of TNF, IL-6 and IL-12p40 after infection of RAW264.7 macrophage cells with Ms_Rv2231c." (PMID 38698289, 2024). "Not only have type-1 interferons been found to inhibit protective cytokines (IFNγ, TNF, IL-12, IL-1α, IL-1β), but they also contribute to spread of infection and lung inflammation by increasing accumulation of myeloid cells." (PMID 39717773, 2024). "In patients with high-risk of infection, anti-TNF seem to be reasonably safe and in particular, as first-line therapy, ETN confirms a trend of lower risk of infections, while ABA can be suggested as a second line therapy." (PMID 38979406, 2024). "The results showed that on both days 3 and 5, the 10 mg/kg or 100 mg/kg probenecid-treated mice had significantly (p < 0.05) reduced IL-6, TNF-α, and IL-1β when compared to the infection control mice." (PMID 38275962, 2024). "Our analysis revealed that LV infection considerably increased the expression of TNF-α, IL-β, and IL-8 genes while levels of IL-6 were unchanged in 22RV1 cells relative to the uninfected cells." (PMID 39427065, 2024).